FBXO10 (F-box protein 10)
Description:
Substrate-recognition component of the SCF (SKP1-CUL1-F-box protein)-type E3 ubiquitin ligase complex. Mediates the ubiquitination and degradation of BCL2, an antiapoptotic protein, thereby playing a role in apoptosis by controlling the stability of BCL2. Targets also the receptor for advanced glycation end products RAGE for ubiquitination and subsequent lysosomal degradation. Directly controls HGAL/GCSAM ubiquitination and degradation and thereby decreases BCR signaling.
Synonyms: FBX10; PRMT11
Tractability: PROTAC: its protein half-life has been measured.
Gene: Protein-coding gene on chromosome 9 (37,510,892 to 37,576,380, reverse strand). Ensembl gene ENSG00000147912.
Subcellular location: Cytoplasm
Subcellular location (Human Protein Atlas): Cytosol; Nucleoplasm
Pathways (Reactome):
Immune System: Antigen processing: Ubiquitination & Proteasome degradation
Metabolism of proteins: Neddylation
Gene Ontology:
Molecular function: protein binding; ubiquitin-protein transferase activity
Biological process: regulation of apoptotic process; ubiquitin-dependent protein catabolic process; protein ubiquitination; SCF-dependent proteasomal ubiquitin-dependent protein catabolic process
Cellular component: cytoplasm; cytosol; SCF ubiquitin ligase complex; ubiquitin ligase complex
Genetic constraint (gnomAD): Loss-of-function variants: 39 observed, 78.72 expected, observed/expected ratio (o/e) 0.5, 90% interval 0.38 to 0.65. The upper end of that interval is the gene's LOEUF score, 0.65, which puts it in group 2 of 6, group 1 being the genes least tolerant of losing a copy. Missense variants: 1,024 observed, 1,294.1 expected, observed/expected ratio (o/e) 0.79, 90% interval 0.75 to 0.83. Synonymous variants: 449 observed, 500.65 expected, observed/expected ratio (o/e) 0.9, 90% interval 0.83 to 0.97.
Homologues: Orthologues: chimpanzee FBXO10 (99% identical), macaque FBXO10 (99% identical), dog FBXO10 (96% identical), rabbit FBXO10 (95% identical), mouse Fbxo10 (94% identical), rat Fbxo10 (93% identical), pig FBXO10 (90% identical), guinea pig FBXO10 (88% identical), tropical clawed frog fbxo10 (64% identical), zebrafish fbxo10 (52% identical), Drosophila melanogaster FBXO11 (19% identical), Caenorhabditis elegans dre-1 (17% identical), and 1 more. Paralogues in human: FBXO11 (20% identical).
Diseases named in the same sentence as FBXO10 in open-access papers:
FBXO10 is named in the same sentence as 29 diseases in open-access papers, as found by Europe PMC text mining. Sharing a sentence is not in itself a finding about the gene and the disease. The quoted sentences say what the papers report.
breast carcinoma (4 papers, 2011 to 2024). "PRMT11, also known as FBXO10, is less studied now, but previous studies have shown that human breast cancer susceptibility-related SNP rs7042509 is present in PRMT11." (PMID 38911125, 2024). "Mcs5a influences tumor progression via the immune system (T cells) in a FBXO10-dependent manner – analogous to a mechanism in human T lymphocytes that is associated with human breast cancer risk." (PMID 31139207, 2019). "Specific T-cell phenotypes are also under control of the synthetically interacting Mcs5a elements that control Fbxo10 transcript levels and mammary carcinoma multiplicity." (PMID 21846333, 2011). "This, together with the observation that Fbxo10 differential expression manifests only in T cells, led to the hypothesis that Mcs5a does not solely function in the mammary parenchyma to modulate mammary cancer susceptibility but instead acts through the immune system." (PMID 21846333, 2011).
lymphoma (4 papers, 2020 to 2022). A malignant (clonal) proliferation of B- lymphocytes or T- lymphocytes which involves the lymph nodes, bone marrow and/or extranodal sites. "Another role identified for FBXO10 in human lymphoma cell lines is in the negative regulation of BCR signalling via BCR signalling-induced membrane re-localisation followed by degradation of human germinal-centre associated lymphoma (HGAL, also called GCET2) protein levels." (PMID 33914737, 2021). "When FLAG-tagged FBXO10 was expressed in HEK293T cells, the E54K substitution decreased immunoprecipitation of endogenous SKP1 to a similar extent as the partial loss-of-function R44H FBOX mutation previously characterised in a human lymphoma." (PMID 33914737, 2021). "In human lymphoma, FBXO10 binds antiapoptotic protein BCL‐2 and accelerates its degradation." (PMID 34492157, 2021). "FBXO10 functions as a potential tumor suppressor in human lymphoma cells." (PMID 34492157, 2021). "FBXO10 binds to the anti-apoptotic oncoprotein BCL-2 and promotes its degradation, thereby initiating cell death in lymphomas." (PMID 32545767, 2020). "FBXO10 and FBXO11 bind to BCL2 and BCL6, respectively, resulting in their ubiquitination and promoting their degradation, thereby regulating the levels of BCL2 and BCL6 proteins in lymphoma cells." (PMID 36644760, 2022).
mantle cell lymphoma (2 papers, 2021). Mantle cell lymphoma is a rare form of malignant non-Hodgkin lymphoma affecting B lymphocytes in the lymph nodes in a region called the ``mantle zone''. "Low FBXO10 expression levels and loss-of-function mutations in the FBXO10 gene have been identified in mantle cell lymphoma and DLBCL, respectively." (PMID 33923680, 2021). "Low FBXO10 mRNA resulting in high BCL2 also appears to drive accumulation of mantle cell lymphomas (MCL) derived from marginal zone or memory B cells." (PMID 33914737, 2021).
autoimmune disease (1 paper, 2021). A disorder resulting from loss of function or tissue destruction of an organ or multiple organs, arising from humoral or cellular immune responses of the individual to their own tissue constituents. "Our interest in FBXO10 was stimulated by the identification of a very rare, predicted damaging, missense variant E54K inherited in homozygous state from healthy heterozygous parents in a child with multiple autoimmune diseases and possible learning difficulties (unpublished data)." (PMID 33914737, 2021).
Cognitive impairment (1 paper, 2021). Abnormal cognition is characterized by deficits in thinking, reasoning, or remembering. "Here, we explored the role of FBXO10 and RAGE in chronic unpredictable stress (CUS)‐induced behavioral despair, cognitive impairment, neuroinflammation, and the polarization microglia." (PMID 34492157, 2021). "FBXO10 overexpression or RAGE knockdown inhibited proinflammatory cytokine release, promoted BDNF expression, mitigated the depressive‐like and cognitive impairment behaviors, and affected the polarization of microglia induced by CUS exposure." (PMID 34492157, 2021). "FBXO10 overexpression or RAGE knockdown inhibited proinflammatory cytokine release, promoted BDNF expression, mitigated the depressive‐like and cognitive impairment behaviors, and inhibited the polarization of M1 microglia." (PMID 34492157, 2021).
depression (1 paper, 2021). "In summary, we confirmed that FBXO10 triggered degradation of RAGE protein by ubiquitination also was involved in depression." (PMID 34492157, 2021). "Considering the interaction between FBXO10 and RAGE in BV2 cells and the strong association between RAGE and depression, we speculated that FBXO10/RAGE axis may play a role in depression." (PMID 34492157, 2021). "Our results revealed that M1 phenotype microglial was increased in the medial PFC after CUS exposure and FBXO10/RAGE axis could promote microglial polarization from the M1 phenotype to the M2 phenotype in vitro and in vivo, which may provide potent therapeutic strategies for depression." (PMID 34492157, 2021).
hepatocellular carcinoma (1 paper, 2025). A malignant tumor that arises from hepatocytes. "These complementary genetic interventions demonstrate that FBXO10 functions as a growth-promoting oncogene in hepatocellular carcinoma progression." (PMID 40699790, 2025). "Aberrant ubiquitination drives hepatocellular carcinoma (HCC) progression, yet the role of FBXO10—a key F-box E3 ubiquitin ligase component—remains uncharacterized." (PMID 40699790, 2025).
malignant mesothelioma (1 paper, 2020). A malignant neoplasm of the pleura or peritoneum, arising from mesothelial cells. "Using whole exome sequencing of five WDPMs of the peritoneum, we have identified distinct mutations in EHD1, ATM, FBXO10, SH2D2A, CDH5, MAGED1, and TP73 shared by WDPM cases but not reported in malignant mesotheliomas." (PMID 32545767, 2020). "Mutations in FBXO10, SH2D2A, and TP73 has not been reported in any malignant mesotheliomas." (PMID 32545767, 2020).
peritoneal mesothelioma (1 paper, 2020). A benign or malignant mesothelial neoplasm that arises from the peritoneum. "Notably, we found WDPM specific mutations in EHD1, FBXO10, CHD5, MAGED1, ATM, and TP73 genes that were absent in peritoneal mesothelioma." (PMID 32545767, 2020).
thyroid carcinoma (1 paper, 2025). "Conversely, FBXO10 showed significant downregulation in kidney renal clear cell carcinoma (KIRC) and thyroid carcinoma (THCA) tissues." (PMID 40699790, 2025).
tumor (5 papers, 2019 to 2025). "Functionally, FBXO10 silencing suppressed HCC cell proliferation while its overexpression promoted tumor growth." (PMID 40699790, 2025). "To assess the FBXO10 expression patterns across human malignancies, we analyzed tumor and normal tissue data from the TIMER database." (PMID 40699790, 2025). "For HCC-specific validation, an integrated analysis of the UALCAN and GEO datasets revealed substantially elevated FBXO10 mRNA and protein levels in the tumor versus normal liver tissues." (PMID 40699790, 2025). "Emerging evidence suggests that FBXO10 may serve as a tumor suppressor in lymphoid malignancies." (PMID 40699790, 2025). "Transcriptomic data from public databases (TIMER, UALCAN, GEO) revealed significant FBXO10 upregulation in HCC tissues, with elevated expression predicting advanced tumor stage, metastasis, and reduced survival." (PMID 40699790, 2025). "Diverging from canonical F-box protein functions in proteasomal substrate degradation, FBXO10 exhibits a non-degradative oncogenic mechanism in HCC by stabilizing FRMPD1 through K63-linked polyubiquitination—a functional dichotomy contrasting with its tumor-suppressive role in lymphoid malignancies." (PMID 40699790, 2025). "Among the possible mechanism at the origin of BCL-2 overexpression, the E3 ubiquitin ligase, F-box only protein 10 (FBXO10), that targets BCL-2 for UPS-mediated degradation, is downregulated in MCL tumor cells." (PMID 32545704, 2020). "We first examined genes that may render cell-growth advantage through analysis of our CRISPR/Cas9 perturbation screen in JeKo-1 cells and found that many critical tumor suppressors were located on chr9, including CDKN2A, SMARCA2, FBXO10, and TOR1B (z score ≥ 1)." (PMID 34882582, 2022).
cancer (2 papers, 2022 to 2025). A tumor composed of atypical neoplastic, often pleomorphic cells that invade other tissues. "While F-box family members like FBXL16 predominantly regulate proteasome-dependent processes in cancers, the FBXO10–FRMPD1 axis defines a unique oncogenic pathway in hepatic malignancies." (PMID 40699790, 2025).
FBXO10 also shares sentences with these, for which no sentence is quoted: B cell lymphomas (1 paper); bladder urothelial carcinoma (1); breast invasive carcinoma (1); cervical squamous cell carcinoma (1); cholangiocarcinoma (1); colon adenocarcinoma (1); endocervical adenocarcinoma (1); esophageal carcinoma (1); head–neck squamous cell carcinoma (1); infection (1); Infertility (1); lung adenocarcinoma (1); lung squamous cell carcinoma (1); ovarian carcinoma (1); rectal adenocarcinoma (1); stomach adenocarcinoma (1); uterine corpus endometrial carcinoma (1).